INS (insulin)
Diseases named in the same sentence as INS in open-access papers (continued):
Sharing a sentence is not in itself a finding about the gene and the disease.
hypogonadism (continued). "Thus, ketosis seems to be an alternative pathway for suppling energy in those with IR hypogonadism, mimicking similar metabolic effects of insulin but at a basic control level, bypassing the complex signaling pathway of insulin." (PMID 37367840, 2023). "We hypothesized that a complex bidirectional relationship between insulin resistance and metabolic hypogonadism was controlled in one direction." (PMID 36675601, 2023). "Thus, the production of KB is exclusive to IR hypogonadism, in which insulin is inactive and cannot inhibit ketogenesis." (PMID 35887101, 2022). "Hence, it was reported that testosterone enhances insulin sensitivity in obese men with hypogonadism by decreasing fat mass, increasing lean mass, decreasing free fatty acids and suppressing inflammation." (PMID 35382807, 2022). "This explains the osteoporosis in hypogonadism, which is strongly related to testosterone deficiency, independent of insulin activity." (PMID 36361519, 2022). "Thus, the livers of males with IR hypogonadism are more prone to lipogenesis, since the higher insulin levels are, the stronger the stimulation of lipogenesis." (PMID 36361519, 2022). "Especially, case 3 was overweight, showed hypogonadism, and had high fasting insulin which could be attributed to the patient’s elevated levels of serum GH, IGF-1, and PRL." (PMID 35002961, 2021). "Thus, the liver of males with IR hypogonadism is more prone to lipogenesis than that in males with IS hypogonadism; therefore the higher the insulin levels, the stronger is the stimulation of lipogenesis with increased triglycerides up to 211 mg/dL." (PMID 29867095, 2018). "Since different metabolic pathways can be altered in hypogonadic males showing normal or high insulin, their identification could help to improve diagnosis, therapy and monitoring of hypogonadism." (PMID 29844353, 2018). "Interestingly, through MataboAnalyst 3.0 it clearly appears that in insulin-resistant hypogonadism lipid metabolism represents the main alternative energy source to glucose pathways." (PMID 29867095, 2018). "For instance, the prevalence and magnitude of hypogonadism among unselected adult insulin-resistant males, as well as its quantitative association with diminished insulin sensitivity have not been reported to our knowledge." (PMID 29998109, 2018). "On the other hand, according to a meta-analysis, hypogonadism could contribute to the accumulation of excess fat and to the reduction of insulin-sensitive muscular mass." (PMID 29324787, 2018). "Given HOMA-IR and fasting insulin had been reported in literatures as valuable biomarkers of low testosterone, we compared the predictive ability of TyG and these two indices for incidence hypogonadism." (PMID 29158535, 2017). "Recent evidence suggests that in hypogonadism, metabolic alterations occurs through different mechanisms depending on whether insulin levels are low or normal, classifying hypogonadal patients into insulin-resistant (IR) and insulin-sensitive (IS) categories." (PMID 37367840, 2023). "In particular, some causes associated with the pathophysiological mechanisms are anorexia, inflammation, hypogonadism, lack of activity, hypovitaminosis D, loss of motor neurons, insulin resistance, poor blood flow to the muscle, mitochondrial dysfunction, and genetics." (PMID 34884255, 2021). "Thus, the present observations in the first stage of hypogonadism, when insulin levels are mostly normal, may have an impact not only on diagnosis and prognosis but also on drug treatment efficacy and safety." (PMID 29844353, 2018). "In IS hypogonadism before TRT treatment, glucose is used as the main biofuel in muscle, adipose and liver, being insulin active." (PMID 37367840, 2023). "Low BMD in AN is considered multifactorial and related to lower BMI, lower lean mass, hypogonadism, Growth Hormone resistance and low IGF-1, high cortisol levels, high PYY levels, and low levels of leptin, oxytocin, insulin and amylin." (PMID 37393263, 2023).
hypogonadism (continued). "In IS hypogonadism before TRT, glycolysis and glutaminolysis produces energy since insulin promotes glutaminolysis, while in IR, the main source of energy is gluconeogenesis through the degradation of BCAAs and the malate–aspartate shuttle." (PMID 37367840, 2023). "In conclusion, the restoration of testosterone values in hypogonadism gives better results in IS than in IR patients: in IS, TRT restores most of the metabolic pathways, while in IR TRT impairs insulin, and when insulin is inactive TRT activates an ancestral molecular mechanism to produce energy." (PMID 36361519, 2022). "Other causes of the wasting are an inadequate calorie intake, reinforced by a diminished appetite due to uremia, multiple comorbid hormonal disorders (insulin and insulin IGF-1 resistance, hypogonadism, hyperparathyroidism) and metabolic acidosis, inhibiting protein synthesis." (PMID 32795277, 2020). "Most likely, this is a consequence of a significantly reduced GLUT4 expression in muscle and adipose tissue in men with IR hypogonadism independent of circulating insulin levels." (PMID 29867095, 2018). "It is of note that plasma cholesterol is approximately similar to the levels recorded in IS hypogonadism (ranging between 213 to 243 mg/dL) indicating that insulin does not significantly influence this metabolism in IR hypogonadism." (PMID 29867095, 2018). "In addition, it has been shown that men with functional hypogonadism and low serum testosterone levels (<16 nmol/L) were more likely to develop T2DM, which is characterized by increased glucose synthesis in the liver and decreased insulin sensitivity." (PMID 41303064, 2025). "In particular, it remains crucial to distinguish between patients with IS hypogonadism and IR hypogonadism because the presence or the absence of insulin—even when testosterone is restored—might play a role in metabolism." (PMID 37367840, 2023). "This evidence supports the hypothesis that, over time, hypogonadism switches from IS to IR, and in the latter case most of the insulin-related metabolisms are not reactivated, at least within 60 days of TRT." (PMID 36361519, 2022). "Moreover, the hypogonadism of sheep or rats lacking pancreatic insulin secretion can frequently but not always be ameliorated by central administration of insulin." (PMID 25946091, 2015). "Thus, testosterone coadministration, which is commonly used to reestablish testosterone levels in hypogonadism, must take into account whether or not insulin is still active." (PMID 37367840, 2023). "However, recent evidence suggests that the metabolic alterations revealed in hypogonadism occur through different mechanisms, depending on whether patients have high or low insulin levels (regardless of diabetes)." (PMID 36361519, 2022). "However, as for insulin and T2DM, the main link between leptin and hypogonadism could be represented by leptin resistance, leading to either defects in the intracellular signaling of the leptin receptor or an abnormal leptin transport across the blood–brain barrier." (PMID 31817436, 2019).
epilepsy (56 papers, 2011 to 2026). A brain disorder characterized by episodes of abnormally increased neuronal discharge resulting in transient episodes of sensory or motor neurological dysfunction, or psychic dysfunction. "Insulin-related type 1 diabetes is positively associated with the risk of epilepsy, and shares genetic or autoimmune factors with epilepsy." (PMID 35624482, 2022). "We focused our analysis on the PI3K/Akt, Wnt, insulin, and the mTOR pathways that are linked to both epilepsy and GSK-3 function." (PMID 30237424, 2018). "Additionally, other high protein diets, such as the ketogenic diet and the Modified Atkins diet, have been associated with better effects on adolescents with epilepsy, with the ketogenic diet to have been related to reduced weight and fasting insulin and HOMA-IR levels in obese teenagers." (PMID 33435217, 2021). "Children with epilepsy had higher fasting insulin and a worse lipid profile than controls." (PMID 42104025, 2026). "TRIP10 encodes a cytoskeletal binding protein involved in endocytosis that suppresses glucose uptake in response to insulin signaling, GPR108 encodes an orphan G-protein-coupled receptor, and SIK1 encodes a salt-inducible kinase with roles in cancer, epilepsy, and myeloid signaling." (PMID 39302339, 2024). "Studies have shown that the insulin signaling pathway is closely related to epilepsy." (PMID 33441699, 2021). "Interestingly, in addition to treating epilepsy, KD was also the standard treatment for DM until the advent of insulin treatment." (PMID 31581549, 2019). "Several peripheral peptide hormones involved in the control of food intake and metabolism (e.g., leptin, adiponectin, NPY, insulin, ghrelin) that are influenced by the KD also possess antiseizure properties and, as such, are promising candidates for future research on new treatments for epilepsy." (PMID 35276837, 2022). "In addition, both energy homeostasis and oxidative stress might share a common pathway in epilepsy, since our study found that the CoQ10 level was significantly positively correlated with insulin level." (PMID 34574891, 2021). "All had severe microcephaly (median standard deviation score –6.2, IQR –6.5 to 6.1), epilepsy diagnosed in the neonatal period (range 1–7 months), and neonatal/early-onset diabetes (age at diagnosis range 4 weeks to 20 months) that was treated with a full replacement dose of insulin." (PMID 33164986, 2020). "Our results proved that XYC exerted favorable effect on epilepsy by modulating the gut microbiota and serum lipid metabolic, especially neuroinflammation and glycerophospholipid metabolism by regulating the AKT1, INS and IL-6 expression levels." (PMID 40880740, 2025). "Notably, AKT1, INS, and IL-6 emerged as central nodes, which were functionally associated with lipid metabolic and inflammation processes, particularly glycerophospholipid metabolism, suggesting their potential as key therapeutic targets of XYC for epilepsy treatment." (PMID 40880740, 2025). "In addition, AEDs could result in the alteration of insulin homeostasis in patients with epilepsy." (PMID 34574891, 2021). "After symptomatic treatment with neurotrophic agents and insulin for glycemic control, clinical manifestations improved, with no recurrence of epilepsy." (PMID 41884135, 2026). "Whether the dysregulation of insulin levels is influenced by epilepsy itself, the types of AEDs used, or both, has not been fully studied." (PMID 34574891, 2021).
hepatic (56 papers, 2006 to 2026). "FFA affects on various signal pathways that inhibit intracellular action of insulin; therefore, it is assumed to play a pathogenic role in both systemic and hepatic IR." (PMID 26039731, 2015). "Overall, both enhanced ER stress and PKCε overactivation caused hepatic IR in SelSH-KO mice, resulting in suppression of hepatic glycogen synthesis and glucose uptake as well as stimulation of hepatic gluconeogenesis, which led to decreased glucose tolerance and insulin sensitivity." (PMID 35347118, 2022). "Liver inflammation at the time of injury has further been shown to influence serum fatty acid levels, mesenteric fat, insulin resistance and, most importantly, worsened SCI outcomes." (PMID 40714859, 2026). "Excessive dietary Ile promoted liver inflammation and interleukin-6 release (P < 0.05), which acted on the pancreas to enhance insulin secretion." (PMID 41668211, 2026). "The liver sphingolipids dCer(22:0) and dCer(24:1) are known to be negatively correlated with whole-body insulin sensitivity and hCer(22:0) and lCer(24:0) with liver inflammation." (PMID 40044043, 2025). "ME/CFS is thus portrayed by insulin resistance and systemic inflammation, with liver inflammation and dysfunction likely affecting lipid metabolism and the balance between HDL and LDL cholesterol." (PMID 40537675, 2025). "Hepatic IR exerts an impact on insulin-mediated glucose homeostasis, influencing the augmented influx of free fatty acids (FFA)." (PMID 40310144, 2025). "Hepatic IR not only chronically up‐regulates gluconeogenesis, but also decreases insulin‐stimulated net glycogen synthesis and glucose uptake, in turn raising postprandial glucose production in a mouse T2DM model." (PMID 39855896, 2025). "Accordingly, IGT typically arises from peripheral IR or a reduction in second-phase insulin release, whereas IFG is mainly caused by impaired insulin suppression of basal glucose output due to hepatic IR or decreased basal insulin secretion." (PMID 39183283, 2024). "More specifically, we discuss the effects of human immunodeficiency virus (HIV), herpes, hepatitis, influenza, respiratory syncytial virus (RSV), and SARS-CoV-2 viruses on insulin sensitivity and BBB function and the proposed underlying mechanisms." (PMID 36768699, 2023). "In this review, we discuss the effects of human immunodeficiency virus (HIV), herpes, hepatitis, influenza, respiratory syncytial virus (RSV), and SARS-CoV-2 viruses on insulin sensitivity and BBB function and the proposed underlying mechanisms." (PMID 36768699, 2023). "The dysregulation was further demonstrated with a significant reduction in hepatic IR expression and a significant increase in blood insulin levels." (PMID 38075064, 2023). "Chronic low-grade inflammation leads to impaired insulin signaling, thereby promoting the progression of hepatic IR." (PMID 36265585, 2022). "In 2003, the Government Primary Health Center in Thiruvananthapuram, India, administrated insulin instead of the hepatitis B vaccine for children." (PMID 36124173, 2022). "Prediabetic NZO mice revealed increased HGP unstimulated and even after insulin stimulation, which indicates hepatic IR, while co-stimulation with insulin counteracted the 5-HT-mediated response." (PMID 35742878, 2022). "For example, amongst patients with haemochromatosis undergoing OGTT, hepatic iron overload is reported to result in impaired insulin extraction." (PMID 26347777, 2015). "Additional enriched pathways encompassed thyroid hormone signaling, human immunodeficiency virus 1 infection, insulin signaling pathway, hepatitis B, MAPK signaling pathway, autophagy, herpes simplex virus 1 infection, hepatitis C, human papillomavirus infection, and apoptosis." (PMID 41332661, 2025). "Hepatitis B vaccines were stored along with insulin and administrated to children mistakenly." (PMID 36124173, 2022).
hepatic (continued). "A number of studies conducted in NAFLD patients showed both an impaired ability of insulin to suppress endogenous glucose production (indicating the presence of hepatic IR) and approximately 50% reduction in glucose disposal (a measure of whole-body insulin-sensitivity)." (PMID 35268466, 2022). "In contrast to the down-regulation of PC aa C42:2 described in cows with hepatic lipidosis, this metabolite was increased in PL ponies, which may also be an indicator of an hepatic insulin sensitivity." (PMID 33509165, 2021). "Hepatic IR increases basal VLDL production, and insulin-dependent suppression of VLDL secretion is impaired." (PMID 37110230, 2023). "The mechanisms by which HCV may promote T2D include impairment of the insulin signaling pathway by viral proteins and HCV-induced liver inflammation resulting in the release of pro-inflammatory cytokines and chemokines that interfere with insulin signaling." (PMID 29258547, 2017). "Although not dynamic measurements of insulin sensitivity/resistance are available for those experiments, the metabolic changes observed are suggestive of hepatic IR." (PMID 28666456, 2017). "In addition, low-dose insulin-mediated suppression of EGP was decreased in patients with NASH, consistent with hepatic IR (% EGP suppression: 41.0 ± 4.3 vs. 70.2 ± 9.5%; p = 0.008)." (PMID 24962805, 2014).
morbid obesity (56 papers, 2007 to 2025). An excess of body weight, normally defined as an individual with a body mass index greater than 35 or a body weight greater than one hundred percent of ideal body weight. "We and others have shown that the increased insulin-stimulated brain GU is reversible and ameliorates after weight loss in morbid obesity and reduces already after short-term exercise training in insulin-resistant subjects." (PMID 38651416, 2024). "Pronounced weight loss after gastric bypass (GBP) surgery in subjects with morbid obesity is associated with a marked improvement in insulin sensitivity, lower fasting hyperinsulinaemia, lower postprandial hyperinsulinaemia and a markedly reduced conversion to T2DM over 10 years of follow-up." (PMID 17894830, 2007). "Patients with morbid obesity had statistically significant higher mean serum values of fasting glucose (p = 0.002) and uric acid (p = 0.006) as well as parameters associated with insulin metabolism (insulinemia, insulin sensitivity and insulin resistance) (p < 0.05)." (PMID 37109222, 2023). "This study is aimed at comparing the diagnostic profiles of OGTT and HbA1c across BMI categories, with a specific focus on morbid obesity and the potential role of elevated insulin levels in test discrepancies." (PMID 40951687, 2025). "Previously it has been shown that insulin-stimulated GU in the small intestine is significantly impaired in morbid obesity and that GU is improved after bariatric surgery, leading to weight loss." (PMID 39458548, 2024). "In agreement with our data, a relative depletion of TCA cycle metabolites was also seen in a primary cell culture of differentiating insulin resistant subcutaneous adipocytes from fat biopsies of subjects with metabolically unhealthy morbid obesity." (PMID 38840842, 2024). "In fact, it has been shown that patients with morbid obesity have reduced glycine synthesis via SHMTs as well as increased insulin levels." (PMID 36837810, 2023). "Fasting blood glucose, HbA1C, and insulin concentrations were significantly higher in the participants with morbid obesity and they were significantly more insulin resistant with higher values of HOMA-IR and lower Matsuda index." (PMID 35757406, 2022). "In the short term, LSG would provide an effective treatment strategy for patients with morbid obesity and T1DM to achieve body weight loss, improve HbA1c level, and reduce the required daily insulin dose." (PMID 33409743, 2021). "Our results suggest that patients with morbid obesity and worst insulin secretory function and higher fasting glycemia tend to lose more weight after bariatric surgery." (PMID 34456871, 2021). "Metformin is a drug of particular interest in subjects with morbid obesity because of the anti-hyperglycemic, insulin sensitising, and weight-reducing effects." (PMID 30524735, 2018). "Furthermore, participants with morbid obesity had higher blood glucose values after consuming a mixed-meal, indicating significant impairment in insulin-mediated glucose uptake and utilization." (PMID 35757406, 2022). "However, there has been no previous report of the effectiveness bariatric surgery in a case of morbid obesity associated with typical acute-onset T1DM, in which pancreatic β-cells were destroyed and endogenous insulin was depleted." (PMID 33409743, 2021). "However, further research is needed to cover this vast topic because there are more parameters to be studied and other factors such as smoking, alcohol use, morbid obesity, insulin use with GDM, type 1 DM, and type 2 DM." (PMID 33133792, 2020). "The metabolic effect of FGF21 might be attenuated by morbid obesity at baseline; nevertheless, after the excess weight was reduced, the association between FGF21 and insulin secretion was restored." (PMID 32210348, 2020). "Patients were men with morbid obesity and fasting insulin levels >8.6 mU/L." (PMID 32830851, 2020).